EPCAM (epithelial cell adhesion molecule)
Diseases named in the same sentence as EPCAM in open-access papers (continued):
Sharing a sentence is not in itself a finding about the gene and the disease.
colorectal adenocarcinoma (12 papers, 2015 to 2023). The most common type of colorectal carcinoma. "EpMab-16 reacted with endogenous EpCAM specifically in a colorectal adenocarcinoma cell line as determined by flow cytometry and western blot analyses." (PMID 33154781, 2020). "The dissociation constant (KD) for EpMab-16 in a Caco-2 colorectal adenocarcinoma cell line determined by flow cytometry was 1.8×10−8 M, suggesting moderate binding affinity of EpMab-16 for EpCAM." (PMID 33154781, 2020). "Flow cytometry was performed to assess the sensitivity of EpMab-16 in CHO/EpCAM cells and the Caco-2 colorectal adenocarcinoma cell line." (PMID 33154781, 2020). "First, a sensitive and specific anti-EpCAM mAb, EpMab-16, was developed, which exhibited high reactivity for colorectal adenocarcinoma by flow cytometry, western blotting and immunohistochemical analyses." (PMID 33154781, 2020). "The purpose of the present study was to establish an anti-EpCAM monoclonal antibody (mAb) for targeting colorectal adenocarcinomas." (PMID 33154781, 2020). "EpMab-16 also bound to Caco-2 but not BINDS-16 cells, indicating that EpMab-16 was specific for EpCAM in the colorectal adenocarcinoma cell line." (PMID 33154781, 2020). "EpCAM-positiveEVs were particularly high in the Caco-2 cells, confirming the differentiated condition of this type of colorectal adenocarcinoma-derived-cell line." (PMID 31357477, 2019). "The present study aimed to determine whether a novel anti-EpCAM mAb may be useful for treating colorectal adenocarcinoma." (PMID 33154781, 2020). "The present study further investigated whether EpMab-16 induced ADCC and CDC antitumor activity in an EpCAM-expressing Caco-2 colorectal adenocarcinoma cell line." (PMID 33154781, 2020). "Another interesting candidate, mAb 8, is found to target the oncofetal antigen epithelial cell adhesion molecule (EpCAM), which is highly expressed in epithelial carcinomas and also expressed in many cancer types like breast, ovarian, colorectal adenocarcinomas and gastric cancers." (PMID 30072783, 2018). "The formation of spheroids by Caco-2, SW480, and HCT116 colorectal adenocarcinoma cell lines under low-adhesion culture conditions were reported to show a 3-fold higher expression of EpCAM compared to monolayers, but no changes in 19 other markers." (PMID 37303738, 2023). "Two different EpCAM negative cells lines were used to observe potential changes in different cell types: human epithelial cell line HEK 293 T and CRISPR/Cas EpCAM-knockout colorectal adenocarcinoma cell line HCT8 #L1320." (PMID 30185875, 2018).
lymphoma (12 papers, 2008 to 2025). A malignant (clonal) proliferation of B- lymphocytes or T- lymphocytes which involves the lymph nodes, bone marrow and/or extranodal sites. "Thus, bispecific antibodies based on CD3-TCR have become a hot spot in the research of tumor targeting therapy recently, especially anti-CD3/CD20 therapy for lymphoma and anti-CD3/EpCAM for GC." (PMID 40777025, 2025). "Uptake of [125I]I-PIB-Ec1 in EpCAM-negative Ramos lymphoma xenografts was much lower (p < 0.001) than uptake in EpCAM-positive SKOV-3 and OVCAR-3 xenografts." (PMID 32392820, 2020). "EpCAM is highly expressed in most of gastrointestinal tumors and in some carcinomas of the genitourinary tract, but not in most soft-tissue tumors and all lymphomas." (PMID 28088790, 2017). "No EpCAM-labeled epithelial cells were found in the blood of healthy donors (n = 25) or of lymphoma patients (n = 20)." (PMID 22586443, 2012). "All tested lymphomas and tumors from the CNS and soft tissues were EPCAM-negative." (PMID 33003511, 2020). "EpCAM-negative Ramos lymphoma xenografts served as specificity control." (PMID 32392820, 2020). "Most soft tissue tumors and all lymphomas were EpCAM negative." (PMID 18687126, 2008).
renal carcinoma (12 papers, 2006 to 2024). A carcinoma arising from the epithelium of the renal parenchyma or the renal pelvis. "Compared with the CellSearch system, ISET has a higher detection rate for CTCs in RCC and more advantages in detecting renal cancer CTCs with low EpCAM expression." (PMID 34034739, 2021). "In our pilot studies, we examined the expression of EpCAM, MUC1 and cytokeratins in renal carcinoma tissues." (PMID 35054482, 2022). "EpCAM-specific antibodies or combination of antibodies (EpCAM, HER2, and EFGR) are widely used in breast, lung, prostate, ovarian, colon and renal carcinomas." (PMID 35884262, 2022). "The NanoVelcro platform combined with CA9-/CD147-capture antibodies demonstrated significantly higher efficiency for capturing both CTC-mimicking renal cancer cells and RCC CTCs in peripheral blood, compared to the conventional EpCAM-based method." (PMID 27494883, 2016). "The IHC staining results confirmed the correlations between LGALS8, RAB17 and EpCAM and survival of renal carcinoma patients treated with sunitinib, while CD9 failed to achieve significant discriminatory potential." (PMID 23555683, 2013).
adenoma (11 papers, 2012 to 2023). A neoplasm arising from the epithelium. "In addition, some studies showed that the overexpression of EpCAM (epithelial cell adhesion molecule) and Trop2 (adenoma-associated calcium signal transduction) was significantly associated with the invasiveness and proliferation of PAs and that they could be used as predictors of PA recurrence." (PMID 35454025, 2022). "(They analyzed four carcinomas and two adenomas from EPCAM deletion carriers for EPCAM protein expression and allelic deletion status of the EPCAM gene." (PMID 23938213, 2013). "Indeed, when compared to the mucosa of wild-type gp130+/+ mice, we detected increased proportions of DCLK1+ and SiglecF+CD24+EpCAM+ tuft cells in the adenomas of gp130F/F mice, which coincided with an increased abundance of iILC2s, but not nILC2s." (PMID 37898600, 2023). "The Wnt/TA cell population comprised 70% of all EpCAM+ cells in the LApcL intestine but only 33% in the LApc intestine and 28% in the adjacent normal tissue, indicating that Lef1 deletion led to an increase in adenoma cells." (PMID 34788095, 2021). "Therefore, this IHC pattern in an adenoma or CRC could be highly suggestive of a concomitant EPCAM deletion and a useful feature to remember." (PMID 33003511, 2020). "The significant transcriptional downregulation of EPCAM (epithelial cell adhesion molecule; CD326) was confirmed in AIPpos tumors compared to normal pituitaries (P = 0.01) and sporadic adenomas (P = 0.004)." (PMID 30867568, 2019). "Of note, some well-established carcinoma markers, including CD24, CD133, and EpCAM, were not upregulated in adenoma as compared to mucosa." (PMID 37667332, 2023).
clear cell renal cell carcinoma (11 papers, 2006 to 2024). "The significant associations between low EpCAM expression and high tumor grade in clear cell renal cell carcinoma and invasive tumor growth in urothelial carcinoma demonstrates that tumor progression can also go along with EpCAM downregulation." (PMID 38786342, 2024). "Low EpCAM staining was linked to invasive disease in urothelial carcinoma (p < 0.0001) and to high grade in clear cell renal cell carcinomas (p < 0.05)." (PMID 38786342, 2024). "Our recent study on clear cell renal cell carcinoma (ccRCC) indicated the higher membranous expression of EpCAM and its direct significant association with nucleolar grade and tumor necrosis." (PMID 35016698, 2022). "EpCAM expression is also associated with better survival in clear cell renal cell carcinoma patients and is related to shortened survival in node-positive breast cancer patients." (PMID 22482828, 2012). "Its role as a homophilic intercellular adhesion molecule has been reported and justifies its anti-metastatic function and down regulation of EpCAM in metastases of renal clear cell carcinomas and thyroid carcinoma." (PMID 35016698, 2022). "In the kidney, chromophobe carcinoma showed strong EPCAM expression, while clear cell renal cell carcinoma showed a weak staining." (PMID 33003511, 2020). "Interestingly, in the literature, it is reported that E-cadherin and EpCAM genes are repressed by PRC2, and, particularly, it has been found that in renal clear cell carcinomas and UTC, the EpCAM expression levels are associated with improved outcomes." (PMID 37238229, 2023). "The low frequency of EpCAM+ CTCs in the blood samples from kidney cancer patients may be related to the fact that clear cell renal cell carcinoma tissue specimens show low levels of EpCAM." (PMID 33261132, 2020).
oral cancer (11 papers, 2016 to 2026). "High co-expression levels of UBE2C/CD44, UBE2C/CD166 and UBE2C/EpCAM were associated with poor prognosis in oral cancer patients from The Cancer Genome Atlas database." (PMID 32899896, 2020). "Moreover, high co-expression of UBE2C/CD44, UBE2C/CD166 and UBE2C/EpCAM was associated with recurrence in oral cancer patients including TSCC patients." (PMID 32899896, 2020). "Our group has also shown that HSP90- and EpCAM-rich sEVs are preferentially secreted from highly metastatic oral cancers and promote cancer cell invasion, EMT, and the TAM differentiation of macrophages." (PMID 41107546, 2026). "Various EpCAM-targeted immunotherapies that demonstrate promising anticancer activity against oral cancer cells and CSCs, including targeted antibodies, chimeric antigen receptor (CAR) T or NK cells, have been developed." (PMID 39996844, 2025). "The epithelial cell adhesion molecule (EpCAM), a transmembrane glycoprotein, has emerged as a critical player in cancer biology, particularly in oral cancer stem cells (CSCs)." (PMID 39996844, 2025). "The oral cancer buccal mucosa cell lines reported previously have validated the epithelial origin of oral cancer cell lines by staining for cytokeratin 8 and 14 or EpCAM." (PMID 41410801, 2025). "This review highlights the multifaceted roles of EPCAM in regulating oral cancer metastasis, tumorigenicity, and resistance to therapy." (PMID 39996844, 2025). "Nevertheless, we further found that high co-expression of UBE2C and cancer stemness markers, including CD44, D166 and EpCAM, have even worse poor prognosis in TSCC patients, which provided potential diagnostic and prognostic markers in oral cancer patients." (PMID 32899896, 2020). "Moreover, high coexpression of UBE2C/CD44, UBE2C/CD166 and UBE2C/EpCAM genes was associated with overall survival and recurrence in oral cancer patients including TSCC patients from TCGA database, indicating that UBE2C might be involved in controlling cancer stemness of OSCC." (PMID 32899896, 2020). "Some of these pathways have been reported to crosstalk with EpCAM during oral cancer progression." (PMID 39996844, 2025). "(F) Detection of EpCAM+Vim+CD24+ cells in the stroma surrounding an oral cancer tumour specimen." (PMID 37975646, 2023). "In addition, we found that oral cancer EpCAM+/ABCG2+ cells undergo inflammation and bacteria-mediated TS phenotype, which also contribute to rapid tumor progression." (PMID 36248858, 2022). "Based on the multifunction of EpCAM engaged in epithelia, the researches into EpEX and EpICD have been widely reported in various epithelial diseases such as thyroid, prostate, colon, and oral cancer, which emphasized the strong correlation between EpCAM and epithelial diseases." (PMID 31886299, 2019). "We have previously identified both EpCAM and CD24 as CSC markers that, alongside the mesenchymal marker Vimentin, identify EMT CSCs in human oral cancer cell lines." (PMID 37975646, 2023). "Subsequently, using a SCC-25 oral cancer–derived CSC model, we showed that hypoxia/reoxygenation or chemotherapy-induced TS enables ABCG2-positive sub-fraction of EpCAM+/ALDH1+/CD44v3+ CSCs to modulate TME for rapid tumor progression and immune suppression." (PMID 36248858, 2022). "However, the efficacy of EpCAM CAR-T cells, NK cells, and vaccines against oral cancer or CSCs have yet to be characterized." (PMID 39996844, 2025). "The EpCAM gene is more highly expressed in the CSC-like side population (SP) of SAS oral cancer cells than in non-SP cells." (PMID 39996844, 2025). "Given the interest in the therapeutic potential of EpCAM targeted therapies in cancer management and the limited understanding of the role and expression pattern of Ep-ICD in oral cancer, our study helps to shed light on this widely-studied, yet not fully understood protein." (PMID 27421772, 2016).
rectal cancer (11 papers, 2010 to 2025). A primary or metastatic malignant neoplasm that affects the rectum. "Expression of CEA, EpCAM, αvβ6, and uPAR is known to be upregulated by the majority of rectal cancer (associated) cells." (PMID 33799475, 2021). "Rectal cancers treated with neoadjuvant chemoradiotherapy comprised a small subgroup of one study which enumerated CTCs based on EpCAM positivity." (PMID 37627212, 2023). "Previous research has shown that CEA and EpCAM expression is upregulated in rectal cancer cells compared with adjacent pre-existent rectal mucosa." (PMID 33799475, 2021). "Especially, for localized rectal cancer patients, the positive rates of samples with more than 3 CTCs per 5 mL blood by use of microdevice vs. EpCAM-based ones were 100% vs. 47%, respectively." (PMID 24066187, 2013). "A previous pilot study indicated that, like CEA and EpCAM, expression of the rectal cancer-associated membrane protein VEGF is absent in the tumor bed of patients with a pCR." (PMID 33799475, 2021). "Epithelial cell adhesion molecule (EPCAM)-magnetic bead-based enrichment of epithelial cells (which includes tumour cells) combined with cytometric identification (CellSearch system) were used in a study of patients with rectal cancer." (PMID 34321074, 2021). "Furthermore, the CTC counts detected by this device were significantly higher than those by EpCAM bead-based method for rectal cancer patients with various stage." (PMID 24066187, 2013). "Promising targets in rectal cancer included carcinoembryonic antigen-related cell adhesion molecule 5 (CEACAM5, referred to CEA), epithelial cell adhesion molecule (EpCAM), urokinase-type plasminogen activator receptor (uPAR) and αvβ6 integrin." (PMID 34684080, 2021). "Epithelial cell adhesion molecule (EpCAM; CD326) is a cell surface receptor which is abundantly overexpressed in the rectal cancer tissue as compared with adjacent normal tissues, so it can be considered as an ideal CRC biomarker in active targeting." (PMID 34641857, 2021). "The current study is a continuation of this research to further evaluate which of the rectal cancer-associated membrane proteins CEA, EpCAM, αvβ6, and uPAR is the most useful indicator of absence of residual vital cancer cells after neoadjuvant therapy." (PMID 33799475, 2021). "Previous immunohistochemical data demonstrated that CEA and EpCAM expression in rectal cancer cells and adjacent pre-existent mucosa does not change after neoadjuvant therapy." (PMID 33799475, 2021). "Our study demonstrates that the targets CEA and EpCAM are absent or have low expression in the tumor bed of nearly all rectal cancer patients with a pCR." (PMID 33799475, 2021). "Promising targets in rectal cancer include carcinoembryonic antigen-related cell adhesion molecule 5 (CEACAM5, from here on to be referred to as CEA), epithelial cell adhesion molecule (EpCAM), αvβ6 integrin, and urokinase-type plasminogen activator receptor (uPAR)." (PMID 33799475, 2021).
liver fibrosis (10 papers, 2021 to 2025). "Furthermore, the protein levels of EpCAM and ITGA3 in liver‐derived EVs were positively correlated to the severity of hepatic fibrosis and were increasingly associated with the progression of MASLD." (PMID 40313415, 2025). "Additionally, H19 functioned as a competitive endogenous RNA that binds to zinc finger E-box homeobox 1 (ZEB1), leading to increased epithelial cell adhesion molecule (EpCAM) expression and promotion of cholestatic hepatic fibrosis." (PMID 39872125, 2024). "Histologically, reversine significantly decreased the expression of the liver fibrosis markers α‐SMA and Desmin, and decreased the expression of biliary protein markers CK7, CK19, and EpCAM, demonstrating reversine's ability to attenuate DR and fibrogenesis." (PMID 36929584, 2023). "Transcriptional levels of liver fibrosis markers (ACTA2, COL1A1, COL1A2, COL3A1) and ductular reaction markers (EPCAM, KRT7, KRT19) were significantly upregulated in BA." (PMID 36816373, 2023). "Another study revealed that overexpression of lncRNA-H19 downregulated the expression of ZEB1 (E-box-binding homeobox 1) and upregulated expression of EpCAM (epithelial cell adhesion molecule) and SRY (sex determining region Y)-box 9 in a mouse model of cholestatic liver fibrosis." (PMID 37919785, 2023). "In contrast, in a mouse model of liver fibrosis, increased ERK activation was associated with cell proliferation and EpCAM overexpression, though it was not specifically tested if ERK activation caused EpCAM overexpression." (PMID 34209658, 2021).
oral squamous cell carcinoma (10 papers, 2010 to 2026). "Subsequent studies have indicated that EpCAM silencing is linked to its promoter methylation in oral squamous cell carcinoma and metastatic lung cancer." (PMID 38791091, 2024). "This review focuses on the critical role of the Epithelial Cell Adhesion Molecule (EpCAM) in oral squamous cell carcinoma (OSCC), emphasizing its contributions to cancer stem cell (CSC) biology, tumor progression, and therapeutic resistance." (PMID 39996844, 2025). "Anti-human EpCAM antibodies tested for their ability to detect the protein on normal feline mammary and renal epithelial cell lines and neoplastic feline mammary epithelial and oral squamous cell carcinoma cell lines using flow cytometry." (PMID 33614766, 2021).